GNL3 (G protein nucleolar 3)
Description:
May be required to maintain the proliferative capacity of stem cells. Stabilizes MDM2 by preventing its ubiquitination, and hence proteasomal degradation (By similarity).
Synonyms: NNP47; E2IG3; NS; C77032; MGC800; Nug1
Tractability: Small molecule: a structure with a bound ligand is known. PROTAC: UniProt records ubiquitination sites on it; ubiquitination databases record sites on it; its protein half-life has been measured.
Gene: Protein-coding gene on chromosome 3 (52,681,156 to 52,696,160, forward strand). Ensembl gene ENSG00000163938.
Subcellular location: Nucleus; Nucleus, nucleolus
Subcellular location (Human Protein Atlas): Nucleoli rim; Mitotic chromosome; Nuclear bodies
Pathways (Reactome):
Metabolism of RNA: Major pathway of rRNA processing in the nucleolus and cytosol
Gene Ontology:
Molecular function: mRNA 5'-UTR binding; protein binding; RNA binding; GTP binding
Biological process: positive regulation of miRNA transcription; positive regulation of protein localization to chromosome, telomeric region; positive regulation of protein sumoylation; positive regulation of telomere maintenance; stem cell division; stem cell population maintenance; regulation of cell population proliferation
Cellular component: chromosome; extracellular region; membrane; nuclear body; nucleolus; nucleus; nucleoplasm
Genetic constraint (gnomAD): Loss-of-function variants: 41 observed, 38.6 expected, observed/expected ratio (o/e) 1.06, 90% interval 0.83 to 1.38. The upper end of that interval is the gene's LOEUF score, 1.38, which puts it in group 5 of 6, group 1 being the genes least tolerant of losing a copy. Missense variants: 405 observed, 410.67 expected, observed/expected ratio (o/e) 0.99, 90% interval 0.91 to 1.07. Synonymous variants: 154 observed, 139.14 expected, observed/expected ratio (o/e) 1.11, 90% interval 0.97 to 1.26.
Homologues: Orthologues: chimpanzee GNL3 (99% identical), macaque GNL3 (97% identical), dog GNL3 (81% identical), pig GNL3 (79% identical), rabbit GNL3 (77% identical), rat Gnl3 (74% identical), guinea pig GNL3 (72% identical), mouse Gnl3 (72% identical), tropical clawed frog gnl3 (46% identical), zebrafish gnl3 (44% identical), Drosophila melanogaster CG10914 (11% identical), Caenorhabditis elegans noa-1 (10% identical). Paralogues in human: GNL3L (32% identical), GNL2 (25% identical), GNL1 (19% identical), LSG1 (18% identical), MTG1 (14% identical), NOA1 (14% identical).